HS6ST2 (heparan sulfate 6-O-sulfotransferase 2)
Diseases named in the same sentence as HS6ST2 in open-access papers (continued):
Sharing a sentence is not in itself a finding about the gene and the disease.
tumor (11 papers, 2007 to 2023). "The association between HS6ST2 expression and the levels of 22 different tumor-infiltrating immune cells was then studied." (PMID 37932473, 2023). "HS6ST2 expression was correlated with immune cell infiltration, immune-related genes, tumor immune microenvironment, and drug resistance in various cancers." (PMID 37932473, 2023). "Our study reveals that HS6ST2 can function as a prognostic marker in various malignant tumors because of its role in tumorigenesis and tumor immunity." (PMID 37932473, 2023). "In present study, the effects of FAM83H-AS1, miR-545-3p, and HS6ST2 on proliferation, invasion, and tumor growth of NSCLC cells were investigated." (PMID 35260044, 2022). "Single cell analysis of tumor tissues revealed that GC patients with increase of HS6ST2+ tumor cells and SERPINE1+ Møs show unfavorable prognoses." (PMID 36211375, 2022). "In vitro and in vivo evidence indicates that HS6ST2 is essential for vascular development and plays an important role in tumor angiogenesis due to its interactions with several angiogenic growth factors, including FGF2, VEGF, IL8, and IL6, among others." (PMID 34944958, 2021). "HS6ST2 expression in tumor tissue was about 50 fold lower than in normal tissue without any difference between metastatic and non-metastatic tumors." (PMID 27336447, 2016). "The correlation between HS6ST2 expression and clinical characteristics, such as age, gender, tumor location, degree of differentiation, lymph vessel invasion, venous invasion and TNM grade was also evaluated." (PMID 24649258, 2013). "In ovarian cancer, HS6ST1 and HS6ST2 were found to be strongly expressed by tumor cells, although only HS6ST1 was detected in endothelial cells." (PMID 24649258, 2013). "Furthermore, HS6ST2 expression was found to be correlated with immune cell infiltration, MSI status, and TMB across malignancy types, and the effect of HS6ST2 on tumor immunity differed between cancer types." (PMID 37932473, 2023). "Our findings indicate that HS6ST2 may have a role in tumor progression and immune evasion through the regulation of immune-related genes." (PMID 37932473, 2023). "Numerous studies have described that inhibition of HS6ST2 in tumor cells impairs cell migration, invasion, and tumor angiogenesis and may reverse EMT." (PMID 34944958, 2021). "According to these results, HS6ST2 may regulate tumor development via these mechanisms." (PMID 37932473, 2023). "HS6ST2 was found to have a critical role in cancer immunity by modulating TMB, MSI status, and tumor-infiltrating immune cell levels and being a predictive factor across malignancy types." (PMID 37932473, 2023). "Cox regression analyses were performed to identify independent clinical prognostic parameters to construct a combined nomogram which includes the expression of CERCAM, MIA2, HS6ST2, ONECUT2, SOX12, TMEM132A, pT stage, tumor size and ISUP grade." (PMID 35954418, 2022). "Compared with normal kidney tissues, antibody stainings for ANKZF1, CD44, IDUA, KIF20A, PLOD2, and VCAN were high in ccRCC tumor tissues, whereas they were low for CHST6, HS6ST2, NDST3 and FBP1." (PMID 33836688, 2021). "HS6ST2 also regulates the Wnt, TGF-β, and Notch signaling pathways, promoting tumor development." (PMID 37932473, 2023). "Of these, HS6ST2, COL10A1, and NQO1 were significantly up regulated in tumor tissues." (PMID 35260044, 2022).
cancer (10 papers, 2013 to 2025). A tumor composed of atypical neoplastic, often pleomorphic cells that invade other tissues. "In summary, HS6ST2 is discrepancy expressed between malignant and para-cancerous tissues, and there are associations between HS6ST2 and RNA and DNA methylation, as revealed by our initial pan-cancer investigations." (PMID 37932473, 2023). "Thus, emerging evidence suggests an association between HS6ST2 expression and the biological function of cancer cells." (PMID 24649258, 2013). "Moreover, HS6ST2 is positively or negatively associated with prognosis in different cancers." (PMID 37932473, 2023). "We initially conducted a pan-cancer analysis of 33 malignancies from the TCGA database to have a deeper knowledge of HS6ST2 is expressed in different cancer types." (PMID 37932473, 2023). "Our results demonstrated a significant correlation between HS6ST2 expression and outcomes in many types of cancer." (PMID 37932473, 2023). "On the basis of data from various databases, a pan-cancer assessment of HS6ST2 expression in 33 distinct malignancies was conducted, and its expression in LUAD tissues was validated." (PMID 37932473, 2023). "In line with our findings, overexpression of HS6ST2 has been found to be a poor prognostic factor in several malignant tumors." (PMID 34944958, 2021). "HS6ST2 was also investigated as an important gene for TGF-β-induced IL-11 production in highly metastatic MDA-MB-231 (SA) cancer cells." (PMID 24649258, 2013). "Finally, there is enough information on the role of CDKN2A, ZIC2, ELAVL2, and HS6ST2 genes in cancer." (PMID 40361484, 2025). "According to our findings, HS6ST2 also plays a crucial role in cancer immunity." (PMID 37932473, 2023). "Furthermore, we utilized the CCLE database for investigating HS6ST2 expression of several cancer cell lines." (PMID 37932473, 2023). "Compared to para-carcinoma tissues, HS6ST2 expression was upregulated in numerous tumors, and thus, HS6ST2 may function as an oncogene in these malignancies." (PMID 37932473, 2023). "Indeed, the removal of cell surface HS by heparinases potently reduced FGF-2-induced cell proliferation, suggesting the importance of HS6ST2 in augmenting M2 macrophages’ induced cancer cell promotion." (PMID 35954218, 2022). "Emerging evidence suggests that HS6ST2 is involved in biological functions of cancer cells." (PMID 35260044, 2022). "HS6ST2 expression was not only associated with MSI in 5 cancer types and associated with TMB in 10 cancer types, and it's significantly correlated with DNA methylation in 13 types of cancer, but it's correlated with RNA methylation related genes in most cancer." (PMID 37932473, 2023). "Therefore, we downloaded the most recent information from the Genotype-Tissue Expression (GTEx), Cancer Cell Line Encyclopedia (CCLE), and The Cancer Genome Atlas (TCGA) databases to comprehensively examine the expression of HS6ST2 and its relationship with prognosis in 33 cancers." (PMID 37932473, 2023). "Furthermore, evidence suggests that HS6ST2 is also associated with EMT by interacting with TGF-beta, HIF-1, and estrogen/GPER pathways, activation of T lymphocytes, and indirectly related with the PD-1, PDL-1 cancer immunotherapy pathway." (PMID 34944958, 2021). "By evaluating the relationship between promoter methylation and HS6ST2 expression in GSCA data, significant relationships between gene expression and methylation were found in 26 distinct cancer types." (PMID 37932473, 2023). "Finally, our enrichment studies implied that HS6ST2 may influence the pathophysiology and/or etiology of cancer by functioning in RNA processing, gene silencing, epithelial cell differentiation, the cytosolic DNA sensing pathway, antigen processing and presentation, and/or drug metabolism." (PMID 37932473, 2023). "We also determined the correlation between the expression of HS6ST2 and the DFS rate in 33 different cancers." (PMID 37932473, 2023).
cancer (continued). "High expression of CERCAM, HS6ST2, ONECUT2, SOX12 and TMEM132A and low expression of MIA2 related to poor outcomes for progression-free survival and cancer-specific survival." (PMID 35954418, 2022). "The mRNA levels of HS6ST2 in clinical CRC samples and various cancer cell lines were assessed using a microarray analysis and quantitative RT-PCR, respectively." (PMID 24649258, 2013). "Nevertheless, HS6ST2 has not been researched thoroughly in the context of cancer, and its role in carcinogenesis and across cancers remains uncertain." (PMID 37932473, 2023). "Although mounting evidence supports a vital role for HS6ST2 in tumorigenesis of some cancers, no pan-cancer analysis of HS6ST2 has been reported." (PMID 37932473, 2023).
adenocarcinoma (2 papers, 2022). A common cancer characterized by the presence of malignant glandular cells. "Consequently, ligand-target regulated transcriptional reprogramming resulted in HS6ST2 expression in adenocarcinoma cells and SERPINE1 expression in macrophages." (PMID 35954218, 2022). "The ligand-target regulated transcriptional reprogramming resulted in HS6ST2 expression in adenocarcinoma cells, while it may lead to the expression of SERPINE1 in macrophages." (PMID 35954218, 2022). "The top three genes upregulated after castration as compared to adenocarcinomas were the heparan sulfate sulfotransferases HS3ST5 and HS6ST2, and the chondroitin sulfate sulfotransferase CHST11." (PMID 35963852, 2022). "The genes in selected metabolic pathways in adenocarcinoma cells potentially regulated by these ligands were predicted as follows: ETFB, HS6ST2, and NDST1." (PMID 35954218, 2022).
cardiovascular disease (1 paper, 2025). "We found 6 proteins that mediated the PGSCAD’s effect on MACE in EXSCEL (C9, LBP, ITIH4, APOM, CES1, and HS6ST2), providing supporting evidence that they might serve as biomarkers for cardiovascular disease in patients with T2D52–54." (PMID 40032831, 2025).
metabolism disorders (1 paper, 2023). "Furthermore, HS6ST2 knockout mice showed glucose and insulin metabolism disorders." (PMID 37337145, 2023).
HS6ST2 also shares sentences with these, for which no sentence is quoted: osteoarthritis (3 papers); breast carcinoma (2); hepatocellular carcinoma (2); metastatic tumors (2); anaplastic astrocytoma (1); astrocytoma (1); cartilage tumor (1); cervical squamous cell carcinoma (1); colon adenocarcinoma (1); diffuse large B-cell lymphoma (1); endocervical adenocarcinoma (1); glioblastoma multiforme (1); head and neck squamous cell carcinoma (1); kidney chromophobe (1); lung squamous cell carcinoma (1); lymphoid neoplasm (1); Mendelian diseases (1); mesothelioma (1); ovarian serous cystadenocarcinoma (1); papillary thyroid cancer (1); paraganglioma (1); pheochromocytoma and (1); prostate adenocarcinoma (1); prostate carcinoma (1); rectum adenocarcinoma (1); retinal degeneration (1); Salmonella Infections (1); skin cutaneous melanoma (1); stomach adenocarcinoma (1); thymoma (1).
A further 2 diseases each share a sentence with HS6ST2 in 1 paper.